NTN1 (netrin 1)
Diseases named in the same sentence as NTN1 in open-access papers (continued):
Sharing a sentence is not in itself a finding about the gene and the disease.
Obesity (continued). "Therefore, our first objective was to study whether obesity and its associated pathology T2D influence NTN-1 and NEO-1 circulating levels and to analyze the effect of weight loss on their plasma levels." (PMID 36297056, 2022). "Recently, research by Ramkhelawon has elucidated a pivotal function of netrin-1 in obesity, notably its role in anchoring adipose tissue macrophages within visceral adipose tissue." (PMID 40405979, 2025). "In summary, these studies collectively underscore netrin-1’s integral role in mediating obesity-related inflammation and its influence on the development of the nervous system." (PMID 40405979, 2025). "Several studies report higher serum netrin-1 in individuals with obesity, prediabetes, or newly diagnosed type 2 diabetes, with positive correlations to insulin-resistance indices (e.g., HOMA-IR) and glycemic markers." (PMID 40949120, 2025). "NTN-1 is highly expressed in the adipose tissue (AT) of humans and animal models with obesity, regulating macrophage accumulation and promoting chronic inflammation and insulin resistance." (PMID 36831381, 2023). "Future studies are required to elucidate the role of NTN-1 in the molecular pathophysiology of CC progression, as well as to assess the impact of its downregulation on obesity-related CC." (PMID 36831381, 2023). "The egress of ATMs from adipose tissue to lymph nodes was suggested by a study on Netrin-1, which is upregulated in obesity of mice and humans and promotes retention of ATMs." (PMID 38037591, 2023). "Netrin-1 protein is another factor whose expression is impaired in bone marrow cells in obesity which promotes adipose tissue inflammation and insulin resistance by acting as a macrophage retention signal." (PMID 38037591, 2023). "The serum concentration of Ntn1 was higher in individuals with newly diagnosed T2D (0.33 ± 0.22 ng/mL), in comparison to healthy subjects and individuals with obesity (0.13 ± 0.06 and 0.15 ± 0.07 ng/mL, respectively)." (PMID 36661496, 2022). "Statistically significant differences (p < 0.001) were found in the serum concentration of Ntn1 between the study groups: healthy subjects (0.13 ± 0.06), obesity (0.15 ± 0.07), and newly diagnosed T2D (0.33 ± 0.22)." (PMID 36661496, 2022). "Moreover, weight loss may improve obesity-associated IR through affecting the levels of NTN-1." (PMID 36297056, 2022). "Future studies are required to elucidate the exact role of NTN-1 in monocyte infiltration and accumulation in VAT as well as to assess the impact of its downregulation in the obesity-associated chronic inflammation and IR." (PMID 36297056, 2022). "The targeted deletion of Ntn1 in macrophages reprogramed the phenotype of AT macrophages in obesity, promoting reduced adipose inflammation and a functional enhancement of lipid flow in AT that drove an improved metabolic function." (PMID 36297056, 2022). "Given the numerous studies demonstrating inflammation as a main contributor to obesity-related IR and since NTN-1 plays a critical role in VAT inflammation, these findings point to NTN-1 as an important component in the pathogenesis of IR." (PMID 36297056, 2022). "To simulate the environment found in the VAT during obesity, we studied the effect of adipocyte-derived factors obtained from patients with OB on NTN1 and NEO1 expression levels in macrophages." (PMID 36297056, 2022). "The involvement of NTN-1 in the regulation of multiple inflammation-related pathologies including cardiovascular and hepatic diseases, cancer and obesity has been widely demonstrated." (PMID 36297056, 2022). "Opposite results have been also described, with levels of NTN-1 being decreased in patients with metabolic disorders including obesity and T2D." (PMID 36297056, 2022). "By genetic depletion of netrin-1 coding gene Ntn 1 in a mouse model of obesity, adipose tissue inflammation and insulin resistance were reduced, due to restored migratory capacity and facilitated emigration of ATM." (PMID 34504646, 2021).
Obesity (continued). "Together, these studies indicate that netrin-1 is a key player in obesity-induced inflammation and functionally impacts glucose tolerance." (PMID 35008701, 2021). "In obesity, netrin-1 hinders ATM egress from the VAT, protects ATM from apoptosis, and induces an inflammatory M1-like phenotype." (PMID 35008701, 2021). "Recently, Ramkhelawon and her colleagues showed that, in obesity, netrin-1 plays a pivotal role in the retention of ATMs in visceral adipose tissue (VAT) and promotes not only systemic inflammation but also metabolic dysfunction." (PMID 35008701, 2021). "In mice, deletion of Ntn1 in hematopoietic cells by bone marrow transplantation prevented obesity-induced inflammation and improved insulin resistance." (PMID 31428465, 2019). "We designed the current study to test how targeted deletion of netrin-1 specifically in macrophages alters macrophage accumulation and phenotype in the adipose tissue during obesity." (PMID 31428465, 2019). "Together, these data suggest that netrin-1 expression by macrophages alters both the subtype of macrophages that accumulate in adipose tissue with obesity, and their gene expression profiles." (PMID 31428465, 2019). "Collectively, our data show that targeted deletion of netrin-1 in macrophages reprograms the ATM phenotype in obesity, leading to reduced adipose inflammation, and improved lipid handling and metabolic function." (PMID 31428465, 2019). "To understand how netrin-1 alters the phenotype of macrophages in the VAT during obesity, we performed single cell RNA-sequencing (scRNA-seq) of CD45+ cells isolated from VAT of WT and Ntn1Δmac mice fed HFD, using the 10× Genomics platform." (PMID 31428465, 2019). "Our studies suggested that adipose tissue macrophages that accumulate with obesity are the source of netrin-1 that drives macrophage accrual in adipose tissue and contribute to insulin resistance." (PMID 31428465, 2019). "Netrin-1 likely plays a key role in the retention of macrophages in the visceral white adipose tissue in obesity, promoting insulin resistance, and chronic inflammation." (PMID 29234017, 2017). "The observed increase in circulating Netrin-1 among participants with obesity and insulin resistance aligns with recent literature showing that Netrin-1 expression in adipose tissue macrophages inhibits their emigration, thereby sustaining local inflammation and exacerbating insulin resistance." (PMID 40949120, 2025). "Our findings support the hypothesis that Netrin-1 functions as a pro-inflammatory molecule involved in the retention of macrophages within adipose tissue, contributing to the pathophysiology of obesity-related metabolic dysfunction and insulin resistance." (PMID 40949120, 2025). "Thus, obesity generates a complex molecular disruption where netrin-1, IL-6, hs-CRP, and adiponectin act as key modulators of chronic inflammation and early metabolic dysfunction." (PMID 40949120, 2025). "This study demonstrates that Netrin-1 and adiponectin exhibit opposing serum profiles across a metabolic spectrum—from non-obese individuals to those with preclinical obesity and clinical obesity + insulin resistance." (PMID 40949120, 2025). "The study will direct the research towards other important roles that NTN-1 may play in obesity including the regulation of insulin sensitivity and oxidative stress." (PMID 36297056, 2022). "This hypothesis suggests that NTN-1 may exerts pro-inflammatory actions in poorly vascularized tissues, such as the AT as well as during chronic inflammatory states, as occurs in obesity." (PMID 36297056, 2022). "In this sense, circulating levels of NTN-1 could reflect the degree of insulin sensitivity and potentially serve as a biomarker to indicate the severity of obesity." (PMID 36297056, 2022). "Moreover, the specific myeloid deletion of Ntn1 halved the resident AT macrophages of high-fat diet (HFD)-fed mice, suggesting that during obesity, NTN-1 reprograms the macrophage phenotype." (PMID 36297056, 2022).
Obesity (continued). "Interestingly, NTN-1 is highly expressed in the AT from mice and humans with obesity, promoting the accumulation of macrophages and their switch to the M1 phenotype, and thus resulting in increased inflammation and metabolic alterations." (PMID 36297056, 2022). "In this sense, we suggest that the pro-inflammatory profile acquired by SVFC during obesity may promote the retention of macrophages in VAT by the release of NTN-1, favoring a cycle of inflammatory cascades in the VAT." (PMID 36297056, 2022). "The DNA dosage and EST expression of CNV12, which overlap with an obesity related gene Netrin-1 (Ntn1), were consistent with Ntn1 RNA expression, suggesting the CNV12 might be involved in the expression regulation of Ntn1 and finally influence meat quality." (PMID 26234186, 2015). "Ntn1 was initially identified for its role in axon guidance during nervous system development, which may also promote the retention of adipose tissue macrophages and contribute to insulin resistance in obesity." (PMID 41445197, 2025). "Thus, we first investigated whether the expression of NTN1 and its receptors are influenced by obesity and CC in human VAT." (PMID 36831381, 2023). "A significant increase of NTN1 expression levels was observed, supporting a crosstalk between adipocytes and macrophages, and suggesting that dysregulated adipocytes in obesity may increase the expression of NTN1 in AT macrophages triggering monocyte infiltration and retention in VAT." (PMID 36297056, 2022). "We hypothesized that NTN-1 is mainly produced by immune cells constituting the stromal vascular fraction cells (SVFC) from VAT with an essential role in the infiltration of macrophages through its receptor NEO-1 perpetuating the inflammatory state in obesity." (PMID 36297056, 2022). "Finally, the regulation of immunometabolism through NTN-1 actions may be critical to our understanding of obesity and metabolic dysfunction constituting an important therapeutic approach." (PMID 36297056, 2022). "Interestingly, our single cell RNA-seq data indicate that loss of macrophage-derived netrin-1 results in a marked decrease in the resident adipose tissue macrophage subpopulation, suggesting that netrin-1 also contributes to the expansion of this macrophage subpopulation in obesity." (PMID 31428465, 2019). "However, prospective studies are required to investigate whether netrin-1 reflects tubular dysfunction due to obesity." (PMID 27087488, 2016). "The present study suggests that Netrin-1 disrupts adipogenesis and adipocyte function by inhibiting compensatory adipose remodeling during excessive calorie intake and may be considered a potential therapeutic target for high fat diet-induced obesity and type 2 diabetes." (PMID 41723276, 2026). "The aim of our study was to assess the usefulness of serum t-CAF levels, urinary netrin-1, α-GST, π-GST, calbindin, and calprotectin as a biomarker of early kidney damage in children with simple obesity, and to determine the site of nephron damage." (PMID 39409098, 2024). "Increased expression levels of NTN1 and its receptor NEO1 in the visceral adipose tissue from patients with obesity and colon cancer together with elevated DCC and UNC5B mRNA levels in patients with colon cancer were found." (PMID 36831381, 2023). "Gene expression levels of NTN1 and NEO1 were upregulated (p < 0.05) in the VAT from patients with obesity with the highest expression in the stromovascular fraction cells compared with mature adipocytes (p < 0.01)." (PMID 36297056, 2022). "Myeloid-specific netrin-1 deletion reduces the ATM accumulation in adipose tissue and reprograms the ATM phenotype during obesity." (PMID 35563728, 2022). "Collectively, these findings suggest that NTN-1 regulates VAT chronic inflammation and insulin resistance in obesity." (PMID 36297056, 2022).
Obesity (continued). "To study the expression patterns of NTN1 and NEO1 in the VAT during obesity, we treated adipocytes and monocytes with different inflammation-associated factors." (PMID 36297056, 2022). "To better understand the source of netrin-1 and its effects on adipose tissue macrophage (ATM) fate and function in obesity, we generated mice with myeloid-specific deletion of netrin-1 (Ntn1fl/flLysMCre+/–; Ntn1Δmac)." (PMID 31428465, 2019). "We aimed to assess the usefulness of serum t-CAF, urinary netrin-1, α-GST, π-GST, calbindin, and calprotectin as biomarkers of early kidney damage in obese children and to investigate the relationship between these indicators and the degree of obesity." (PMID 39409098, 2024). "In summary, the findings of our case-control study suggest that NTN-1 is an inflammatory factor with increased circulating concentrations in patients with obesity and mainly secreted by the SVFC from the VAT that favors chronic inflammation and IR in obesity." (PMID 36297056, 2022). "Together, these data suggest that netrin-1 deletion in macrophages reduces the levels of pro-inflammatory lipid mediators in VAT known to contribute to chronic inflammation and insulin resistance in obesity." (PMID 31428465, 2019). "We postulated that the local secretion of netrin-1 by ATMs acts a as “stay put” signal that contributes to a maladaptive immune response in obesity by sustaining the cycle of non-resolving inflammation." (PMID 31428465, 2019). "Therefore, mice lacking netrin-1 in myeloid cells are protected from diet-induced obesity and metabolic dysfunction." (PMID 35563728, 2022).
diabetes (20 papers, 2014 to 2025). "Here novel insights into the molecular mechanisms are provided underlying DE, and the therapeutic potential of targeting DAPK1 and Ntn1 is highlighted to alleviate diabetes-associated central nervous system complications." (PMID 40787892, 2025). "Other studies have characterized the protective effect of netrin-1 on the apoptosis of β-cells, in diabetic retinopathy, diabetic nephropathy, and diabetes-associated myocardial infarction." (PMID 35008701, 2021). "It is important to note that plasma netrin-1 levels has been shown to be markedly decreased in patients with diabetes, and this effect was negatively associated with insulin resistance and glucose homeostasis." (PMID 29059224, 2017). "Second, netrin-1 is also associated with islet dysfunction in diabetes and negatively correlated with hyperglycemia." (PMID 27255377, 2016). "Since diabetes and its co-morbidities are associated with hyperactive inflammation, netrin-1 could be a promising therapeutic candidate that reduces hypoglycemia while also ameliorating inflammation for diabetic individuals." (PMID 35008701, 2021). "This goes in line with previous studies that reported a marked increase of urinary netrin- 1 by proximal tubular epithelial cells in diabetes-induced renal tubular injury." (PMID 40332546, 2025). "In contrast, reduced levels have been observed in more advanced diabetes or β-cell dysfunction, suggesting stage-dependent regulation, differences in inflammatory tone, or exhaustion/adaptation of the netrin-1 axis." (PMID 40949120, 2025). "In diabetes mellitus and its complications, Netrin-1 is highly expressed in obese adipose tissue of humans and mice, causing retention of macrophages for activated inflammation." (PMID 38638604, 2024). "In mice with high-fat diet/streptozotocin-induced diabetes, Netrin-1 treatment increases insulin release from β-cells, promotes islet vascularization, reduces islet macrophage infiltration, and alleviates inflammation." (PMID 38638604, 2024). "A reduction in serum NTN‐1 levels was also observed in patients with subclinical atherosclerosis, type 2 diabetes mellitus, and multiple sclerosis." (PMID 36852451, 2023). "For example, recent studies have revealed pro-angiogenic, anti-apoptotic and anti-inflammatory properties of NTN1 as well as preventing vascular dysfunction in diabetes." (PMID 38371897, 2023). "A down-regulation of netrin-1 has also been observed in inflammatory and autoimmune diseases, such as multiple sclerosis, type 2 diabetes mellitus patients, aneurysmal subarachnoid hemorrhage (Chen J.-L." (PMID 35250531, 2021). "Blood netrin-1, a laminin-related protein, is also increased in individuals with pre-diabetes and with T2D." (PMID 34769081, 2021). "A recent study found netrin-1 plasma levels to be decreased in patients with newly diagnosed diabetes mellitus type 2, and even suggest that netrin-1 should be assessed for its potential in early diabetes screening." (PMID 35008701, 2021). "First, we included drug-naïve, newly-diagnosed patients with type 2 diabetes, minimizing any effect of anti-diabetes medication on serum netrin-1 concentrations." (PMID 30532735, 2018). "For instance, Netrin-1 anti-inflammatory actions were mediated through diabetes-induced COX-2 expression and PGE2 production." (PMID 30320139, 2018). "Taken together, a possible beneficial compensatory response of netrin-1 to the changes that happen early in the time course of diabetes needs to be studied." (PMID 30532735, 2018). "The multiple function of netrin-1 provides a candidate for treatment of persistent corneal epithelial defects in patients with diabetic mellitus." (PMID 29662125, 2018). "As a potential predictive indicator for IFG or type 2 diabetes, netrin-1 has the substantial clinical potential to prevent diabetes or slow its progression." (PMID 30532735, 2018).